INS (insulin)
Diseases named in the same sentence as INS in open-access papers (continued):
Sharing a sentence is not in itself a finding about the gene and the disease.
Insulin resistance (continued). "The improvement of insulin action occurs very early at 3–5 days following LSG with a significant reduction in insulin resistance." (PMID 24694037, 2014). "Insulin resistance, defined as a decrease in cellular responsiveness to insulin signaling, triggers increased insulin secretion, a phenomenon termed “compensatory hyperinsulinemia”." (PMID 25763406, 2014). "These cytokines exert direct actions on adipocytes and other insulin target cells, inducing chronic inflammation and insulin resistance." (PMID 24516630, 2014). "Glimepiride, a third-generation sulfonylurea (SU), exerts its effects mainly by stimulating insulin secretion but has also been shown to have extrapancreatic effect such as improvement insulin resistance." (PMID 24650537, 2014). "In serum, glucose and insulin concentrations were dramatically upregulated compare to wild type mice, indicating that apoE knock-out resulted in glucose uptake impairment and insulin resistance (IR)." (PMID 24526524, 2014). "Type 2 diabetes is a clinical disease characterized by disruption in the metabolism of glucose and lipids, and consequential failure in the production of insulin as well as insulin resistance." (PMID 24521082, 2014). "Insulin stimulated glucose uptake was reduced under lipotoxic conditions indicating development of insulin resistance in myotubes which was restored by NAC treatment indicating reduction in oxidative stress can improve insulin sensitivity." (PMID 24936385, 2014). "Insulin resistance first leads to compensatory oversecretion of insulin by the pancreatic β-cells and, eventually, β-cell exhaustion and development of type 2 diabetes." (PMID 24977043, 2014). "Insulin resistance is a common pathological condition defined as the reduced ability of insulin to produce its biological effects." (PMID 25330241, 2014). "Insulin modulates protein synthesis and degradation in the muscle, and therefore, insulin resistance is found to promote catabolism of the skeletal muscle." (PMID 24783225, 2014). "Several other animal models of insulin resistance including the ob/ob mouse, db/db mouse, Zucker fatty rat, and offspring of malnourished or insulin treated pregnant rats all exhibit increased noradrenergic turnover within the VMH." (PMID 25937836, 2014). "Because insulin resistance is known to precede beta-cell dysfunction in the natural history of T2DM, stratifying individuals on the basis of insulin resistance and insulin secretion measures would ideally identify subjects at different stages of the disease." (PMID 25347846, 2014). "Traditional views of type 2 diabetes pathophysiology indicated peripheral insulin resistance, i.e., the inability of insulin-target tissues to respond properly to the hormone, as the main driver of altered glucose homeostasis." (PMID 25232350, 2014). "This study examined the role of GH and insulin signaling crosstalk in insulin resistance of SGA rats with CUG." (PMID 24963636, 2014). "Studies have shown that branched-chain and aromatic amino acids, as well as C3- and C5-acylcarnitines, can affect insulin sensitivity and markers of insulin resistance." (PMID 24682914, 2014). "It has been demonstrated that a series of molecular alterations in insulin signaling occurs in the setting of insulin resistance, finally resulting in triglyceride accumulation in the liver." (PMID 24688399, 2014). "Insulin resistance is characterized by a decrease in insulin-stimulate glucose uptake in skeletal muscle via glucose transporter 4 (GLUT4) and by impaired suppression of glucose production in liver." (PMID 25140189, 2014). "Insulin resistance (IR) refers to the reduced biological efficacy of insulin on insulin effector organs and the consequent decrease in glucose uptake and elimination in surrounding tissues, including the liver, skeletal muscle and adipose tissues." (PMID 24926351, 2014).
Insulin resistance (continued). "Serum osteocalcin was negatively correlated with fasting insulin and ‘homeostasis model assessment of insulin resistance’." (PMID 24524669, 2014). "In several studies, the relation between low vitamin D levels, insulin resistance and impaired insulin secretion was clearly demonstrated." (PMID 25308347, 2014). "The role of leptin in MS pathophysiology has also been demonstrated; it affects insulin sensitivity, and induces insulin resistance and lipid accumulation." (PMID 25548896, 2014). "In support of these findings, we were unable to observe improvements in body weight or insulin sensitivity by increasing fatty acid oxidative potential with the over-expression of MCD in our model of high fat diet induced insulin resistance." (PMID 25152047, 2014). "Diabetic features in db/db mice follow an age-dependent progression, with early insulin resistance followed by an insulin secretory defect resulting in profound hyperglycemia." (PMID 25723052, 2014). "Compared to healthy European-ancestry participants matched for age and body mass index (BMI), Asian Indian individuals exhibit higher insulin resistance and a greater contribution of insulin resistance—relative to insulin secretion—to T2D pathogenesis." (PMID 24744783, 2014). "They induced different adaptive responses in post-natal glucose metabolism: an early insulin-resistance was induced in enhanced P-D, while S-P developed increased insulin sensitivity." (PMID 25006665, 2014). "These include models of insulin resistance in 3T3-L1 adipocytes, transgenic models in mice, adipose tissue from insulin resistance mice and adipose tissue from insulin resistant humans." (PMID 24752197, 2014). "Previous studies have shown that the combination of HFD and STZ treatment can lead to disorders in glucose and lipid metabolism accompanied by impaired insulin secretion and insulin resistance." (PMID 24968071, 2014). "The pathophysiology of T2D is characterized by insulin resistance and impaired compensatory insulin secretion." (PMID 24586809, 2014). "Obesity is believed to lead to insulin resistance and increased circulating insulin concentrations over time." (PMID 24821545, 2014). "Insulin resistance of peripheral tissues, predominantly muscle, results in impaired insulin stimulated glucose uptake and postprandial hyperglycemia." (PMID 26237392, 2014). "In conclusion, adiponectin and adiponectin receptors improve insulin resistance by modulating triglyceride level and impaired insulin signal transduction." (PMID 24860814, 2014). "Studies in humans and in experimental animal models have shown that IGFBP-2 is a key factor in the insulin-IGF cross-talk and also linked to insulin resistance." (PMID 24725803, 2014). "Insulin resistance is characterized by the inability of a tissue to respond to insulin, which will impair the input of glucose into the cell as well as the sensitivity of IRS/PI3K/NO signaling pathway." (PMID 25352918, 2014). "Fasting blood glucose with plasma insulin and lipids was measured, and insulin resistance (HOMA IR) calculated using the homoeostasis assessment model." (PMID 23751160, 2014). "It is frequently referred to as an “insulin sensitizer” because it lowers circulating insulin levels in settings of insulin resistance and hyperinsulinemia." (PMID 24612549, 2014). "The response of β cells to the progression of T2D begins with an adaptive stage, in which the cells compensate for insulin resistance by over-production and over-secretion of insulin, as well as increasing β cell replication." (PMID 25233132, 2014). "HFD feeding significantly increased serum insulin levels, possibly as a result of elevated serum lipids and induced mild peripheral insulin resistance, as reflected by markedly elevated fasting serum insulin and reduced ISI." (PMID 24759758, 2014).
Insulin resistance (continued). "In 599 healthy adults and after adjustment for age and gender, systolic blood pressure (BP), Homeostasis Model Assessment index for insulin resistance (HOMA-IR) and β cell function (HOMA-β) and fasting insulin were associated with increasing number of alleles." (PMID 24465431, 2014). "Insulin resistance is characterized by a decrease in insulin-stimulate glucose uptake in skeletal muscle via glucose transporter 4 (GLUT4) and by impaired suppression of glucose production in liver tissue." (PMID 25375187, 2014). "Multiple studies have indicated that HMW-adiponectin is the most active form with insulin-sensitising activity, and its circulating levels negatively correlate with obesity, insulin resistance, and coronary artery disease (CAD)." (PMID 25374599, 2014). "In high-fat-diet and normal-weight rodent models, PM2.5 exposure induced insulin resistance by promoting adipose inflammation and through potential disruption of insulin signal transduction." (PMID 24508979, 2014). "Tissue-specific insulin resistance indices and fasting plasma insulin as predictors of total incident CVD events in the 5.9-Years METSIM prospective study, Kuopio, Finland." (PMID 25310839, 2014). "One of the major effects of obesity in the body is the increased levels of insulin, leading to insulin resistance." (PMID 25083180, 2014). "Then, in two mouse models of insulin resistance, leptin-deficiency and high-fat diet feeding, third intra-cerebro-ventricular infusions of FGF19 improved glycemic status, reduced insulin resistance and potentiated insulin signaling in the periphery." (PMID 24567901, 2014). "Here we explore how GLUT4 sorts from the plasma membrane of L6 muscle cells into compartments that define acquisition of insulin responsiveness, and examine if C2-ceramide, which confers insulin resistance, can affect GLUT4 sorting into these compartments." (PMID 24705014, 2014). "Cardiac insulin resistance promotes heart failure: the heart is an insulin-responsive and energy-consuming organ that requires a constant fuel supply to maintain intracellular ATP levels for myocardial contraction." (PMID 25069836, 2014). "Insulin resistance, which signifies reduced sensitivity of insulin-sensitive cells to insulin-mediated actions, has long been recognized as a key factor in the pathogenesis of T2DM." (PMID 25587486, 2014). "Insulin resistance is strongly correlated with liver steatosis, and interventions that ameliorate insulin resistance result in lower insulin levels and decreased liver fat content." (PMID 24632889, 2014). "As expected, increasing BMI exerts a major effect on both insulin resistance and β-cell insulin response, but high levels of androgens seem to affect both sites, i.e. insulin action and insulin secretion, of the glucose metabolism." (PMID 24705280, 2014). "Together, these results demonstrate that fatty acid/fat is essential for the development of insulin resistance induced by the chronic exposure to a pathological level of insulin." (PMID 25055153, 2014). "Pharmacological compounds, such as the thiazolidinediones (TDZ), that target PPARγ activity have thus been exploited as insulin sensitizers, and are now widely used for the treatment of insulin resistance in T2DM patients." (PMID 25405601, 2014). "Second, stress hormones induced by major surgery is known to result in insulin resistance by preventing insulin from suppressing hepatic gluconeogenesis and inducing glucose uptake into skeletal muscle." (PMID 25295519, 2014). "Conversely, in vitro studies showed that NF-κB activation affects TWEAK-induced insulin resistance by attenuating the action of insulin in hepatocytes." (PMID 24565471, 2014). "Dysregulation of the HPA axis as a result of stressor exposure, in conjunction with chronically elevated insulin levels, contribute to the development of insulin resistance, abdominal obesity, as well as metabolic syndrome." (PMID 24801635, 2014).
Insulin resistance (continued). "Up-regulation of IDE activity is an ideal approach in the treatment of insulin-mediated insulin resistance in T2D." (PMID 24740421, 2014). "Recent studies have revealed that FRDA patients exhibit some degree of insulin resistance, suggesting the possibility of an additional role for frataxin in mediating insulin signalling and insulin secretion." (PMID 25198290, 2014). "By contrast, the specific serine phosphorylation of the IRS-1/2 by the c-Jun N-terminal kinase (JNK1) and other protein kinases inhibits insulin-stimulated tyrosine phosphorylation, which correlates closely with insulin resistance." (PMID 25346723, 2014). "While insulin resistance is known as a consequence of obesity, insulin is also critical in the expansion of adipose tissue that typifies obesity." (PMID 24949486, 2014). "In 1929, Root summarized the presence of an inadequately high need for insulin in different diseases, and he called the phenomenon 'insulin resistance' (IR)." (PMID 25608958, 2014). "TNF-α and IL-6, two well-known pro-inflammatory cytokines, affect insulin action and promote insulin resistance." (PMID 24913911, 2014). "These inflammatory molecules are upregulated in insulin-target tissues, including the liver, adipose tissue, and muscles, thus contributing to insulin resistance." (PMID 25214711, 2014). "Recent studies have demonstrated that insulin resistance can develop not only in the classic insulin-responsive tissues, but also in cardiovascular tissues where insulin participates in the development of cardiovascular diseases and hypertension." (PMID 24485020, 2014). "Previous studies have shown that type 2 diabetes usually develops due to insufficient pancreatic insulin secretion to compensate for the existing insulin resistance." (PMID 25174260, 2014). "TNF-α induces hypothalamic and peripheral insulin resistance in rodents and alters insulin sensitivity and glucose homeostasis in humans." (PMID 25258479, 2014). "In other words, insulin plays an essential role in converting nutrients into insulin resistance and then T2DM." (PMID 24741073, 2014). "One model of hyperglycemia-induced insulin resistance involves chronic preincubation of adipocytes in the presence of high glucose and low insulin concentrations." (PMID 25330241, 2014). "According to the European Group for the Study of Insulin Resistance, fasting insulin is the best available simple proxy for insulin resistance, which is defined by presence of fasting hyperinsulinemia." (PMID 25534067, 2014). "During insulin resistance, insulin-mediated anabolic metabolic effects are inhibited in the classic insulin-responsive tissues." (PMID 24485020, 2014). "Prior rodent studies, indicate that TRIB3 overexpression plays a major role in modulating whole-body insulin sensitivity and suggest a possible involvement in the pathogenesis of insulin resistance-related metabolic abnormalities." (PMID 24650557, 2014). "Compared with those fed the SCD, male mice fed the HFD were glucose intolerant and had higher plasma insulin levels, indicative of insulin resistance, during the OGTT after both 4 and 12 weeks of HFD." (PMID 25375135, 2014). "Insulin resistance (IR) is the decrease in the capacity of several tissues to respond to insulin, failing to transport glucose into the cell." (PMID 31667162, 2014). "Likewise, the predisposition in patients with insulin resistance for aging, cancer, liver steatosis, dyslipidemia, atherosclerosis, cardiovascular disease, and why intensive insulin therapy may initially worsen retinophaty, also be at least partially explained." (PMID 25486190, 2014). "For example, in the beta-islet cells of the pancreas, calcium channel antagonism inhibits insulin secretion, producing insulin resistance and hyperglycemia." (PMID 24713415, 2014).
Insulin resistance (continued). "The role of inflammation in the promotion of insulin resistance is also highlighted by evidence suggesting a central role of MAPKs and the IKKβ/NF‐kB pathway in the inhibition of insulin signaling in different tissues." (PMID 24819750, 2014). "Despite higher insulin resistance during the last year of GH treatment, a compensatory insulin secretion was recorded: HOMA-β and INS were higher at T0, and progressively decreased at T6 and T12 (p<0.05), with a stable DI." (PMID 24498035, 2014). "Resistance to insulin was assessed using Homeostasis Model Assessment of Insulin Resistance (HOMA-IR)." (PMID 25560330, 2014). "For example, miRNAs play major roles in pancreatic islet development, β cell dysfunction, insulin synthesis and secretion and insulin resistance." (PMID 25421534, 2014). "From the standpoint of glucose homeostasis and insulin sensitivity, rapamycin and CR have quite divergent effects, with rapamycin treatment resulting in glucose intolerance and hepatic insulin resistance." (PMID 25674466, 2014). "Aside from the FMD procedure, adiponectin levels were measured and insulin sensitivity was calculated through the homeostasis model assessment of insulin resistance." (PMID 26171320, 2014). "Defects in the insulin signaling cascade, which lead to impaired glucose utilization, were believed to play a key role in the pathogenesis of insulin resistance." (PMID 24555840, 2014). "After treatment with FTZ, body weight, levels of serum TG and TC, fasting glucose and plasma insulin and the insulin resistance index were significantly reduced compared to MS rats." (PMID 24555840, 2014). "HOMA-IR is a parameter that can be calculated from serum insulin levels and is regarded widely as a reliable biomarker of insulin resistance." (PMID 25548795, 2014). "Researchers have indicated that a greater body mass is not only accompanied by insulin hypersecretion, but also lower hepatic clearance and by peripheral insulin resistance." (PMID 25114733, 2014). "In T2D, a steady rise in insulin resistance leads to a corresponding increase in fasting insulin levels as the disease progresses." (PMID 25548795, 2014). "Along with this insulin resistance, a relevant role in maintaining hyperglycemia is played by an impaired basal glucose uptake, which was reduced by>30% in relatively non-insulin sensitive organs such as kidney and skin." (PMID 25549240, 2014). "Animal models characterized by reduced-leptin signaling show hyperphagia, obesity, and insulin resistance, and leptin management improves insulin sensitivity and glucose metabolism in these models." (PMID 25202741, 2014). "More precisely, NEFA induce insulin resistance through activation of a serine-kinase cascade, leading to the inhibition of the insulin signaling pathway in adipose tissue, skeletal muscle, and liver." (PMID 25371817, 2014). "Tissue-specific insulin resistance indices and fasting plasma insulin as predictors of incident type 2 diabetes in the 5.9-years METSIM prospective study, Kuopio, Finland." (PMID 25310839, 2014). "For example, PD identified by FPG is related to both hepatic insulin resistance and reduction in first-phase insulin secretion, leading to excessive fasting hepatic glucose production." (PMID 25960777, 2014). "Insulin resistance (IR) and impaired insulin secretion are two major pathophysiological defects in type 2 diabetes." (PMID 25310839, 2014). "HOMA‐IR was calculated from the fasting level of glucose and insulin in 6‐month‐old WT and ksr2−/− mice, revealing significant insulin resistance in the knockout mice." (PMID 24997067, 2014). "Given that transcript level regulation is consistent for both insulin resistant mouse models, the transcript regulation observed in cell culture during insulin resistance is validated." (PMID 25657638, 2014).